ALPK1 (alpha kinase 1)
Diseases named in the same sentence as ALPK1 in open-access papers (continued):
Sharing a sentence is not in itself a finding about the gene and the disease.
gout (continued). "To test if ALPK1-associated cytokine response has relevance in gout, we measured its protein level among thirty male individuals: twenty gouty males who had blood drawn during an acute gouty flare in outpatient clinic, and ten healthy males from the same hospital." (PMID 27169898, 2016). "As hyperuricemia is highly correlated with CKD risk, together with the renal expression of ALPK1, ALPK1 could be a possible susceptible gene for gout/hyperuricemia." (PMID 25326865, 2015). "However, no replication study has been performed to confirm the association between ALPK1 and gout." (PMID 25326865, 2015). "A genomic study analyzed the epistasis of ALPK1 with the loci of GLUT9, ALPK1, SLC22A12, and ABCG2, finding a positive predictive value (PPV ≥ 81%) to measure the risk of gout (OR ≥ 12.30) using variants of these genes in different populations." (PMID 35505381, 2022). "Numerous studies have supported the finding that ALPK1 is correlated with gout, chronic kidney disease, and diabetes using epidemiological, human, animal, and cellular models." (PMID 36139553, 2022). "The findings suggest ALPK1 is a kinase that participates in the regulation of Golgi-derived TNF-α trafficking through myosin IIA phosphorylation in the inflammation of gout." (PMID 27169898, 2016). "Alpha kinase-1 (ALPK1) has shown to be associated with MSU-induced inflammation and gout." (PMID 27169898, 2016). "We hypothesize that ALPK1 participates in the vesicular transport of certain cytokines to the plasma membrane in gout." (PMID 27169898, 2016). "Conceivably, an aberrant ALPK1 might delay normal cytokine response and contribute to chronic gout and tophi, as these were observations in the original affected population." (PMID 27169898, 2016). "Although further studies of ALPK1 are necessary to reveal the relationship between ALPK1 SNPs and gout, our study at least revealed that rs11726117 of ALPK1 is not a strong genetic risk for gout." (PMID 25326865, 2015). "Taken together, these findings suggest that among genes in a gout-susceptibility locus, not ALPK1 but ABCG2 is important as a susceptible gene for gout." (PMID 25326865, 2015). "The increased expression of ALPK1 and SLC22A12 in the blood of patients with gout could be associated with their altered metabolic status, which favors a long-term chronic condition with recurrent acute episodes if hyperuricemia and comorbidities are maintained." (PMID 35505381, 2022). "Although epidemiological and mechanistic studies have implicated ALPK1 in gout, chronic kidney disease, and diabetes, no study has reported whether ALPK1 is directly involved in these inflammatory diseases that contribute to cancer risk." (PMID 36139553, 2022). "Therefore, we speculate that the pathogenesis of gout involves hyperuricemia leading to precipitation of monosodium urate in joints, which triggers ALPK1 to activate proinflammatory cytokine (such as TNF-α) secretion." (PMID 36139553, 2022). "Because ABCG2, a major causative gene for gout, also locates in the gout-susceptibility locus on chromosome 4q, these findings suggest that among genes in a gout-susceptibility locus, not ALPK1 but ABCG2 could be important as a gout-susceptible gene." (PMID 25326865, 2015). "We found endogenous ALPK1, myosin IIA, and plasma TNF-α were higher among gout patients than healthy controls (p < 0.01)." (PMID 27169898, 2016). "Currently, no study has examined the role of ALPK1 in the carcinogenesis of gout, chronic kidney disease, and diabetes, but persistent chronic inflammation may be involved in the carcinogenesis of these diseases." (PMID 36139553, 2022). "Interestingly, three genes (PDZK1, GCKR and HNF4G) associated with urate influenced the risk of gout, but the other five genes (TCF7L2, LRRC16A, ESR1, NRXN2 and ALPK1) did not, suggesting that elevated serum urate concentration is necessary but not sufficient for the pathogenesis of gout." (PMID 28252667, 2017).
gout (continued). "Extracellular TNF-α secretion was significantly reduced by the knockdown assays of endogenous ALPK1 and myosin IIA but not IL-1β thus IL-1β was not followed through into the human assays of gout patients." (PMID 27169898, 2016).
anhidrosis (10 papers, 2019 to 2025). Lack of sweating or the ability to sweat when provoked by the appropriate stimulus. "In this study, we report a 12-year-old male patient with a de novo ALPK1 p.Thr237Met mutation who presented progressive visual impairment, anhidrosis, splenomegaly, and arthralgia, representing the multisystem involvement typical of this condition." (PMID 41235249, 2025). "ROSAH (retinal dystrophy, optic nerve edema, splenomegaly, anhidrosis, and headache) syndrome is a rare genetic disease caused by variants in alpha-kinase 1 (ALPK1) resulting in downstream pro-inflammatory signaling mediated by the TIFA/TRAF6/NF-κB pathway." (PMID 40925900, 2025). "We define a phenotypically distinct autosomal dominant retinal dystrophy syndrome, ROSAH, with features of retinopathy, optic nerve edema, splenomegaly, anhidrosis, and headache in five unrelated families, and show heterozygous (c.710C>T, [p.Thr237Met]) ALPK1 as the causative variant in all cases." (PMID 30967659, 2019).
colorectal cancer (10 papers, 2016 to 2025). A primary or metastatic malignant neoplasm that affects the colon or rectum. "ALPK1-associated cancers include lung cancer, colorectal cancer, breast cancer, oral cancer, and lymphoblastic leukemia." (PMID 36139553, 2022). "As a result, we further explored the mutation sites of ALPK1 in the lung and colorectal cancers of a Taiwanese cohort via HRM analysis." (PMID 27283888, 2016). "In 98 matched colorectal patients, the abundance of F. nucleatum in the tumor tissues of patients with colorectal cancer was correlated with the expression levels of ALPK1 and ICAM1, which were also associated with shorter overall survival time in patients with colorectal cancer liver metastasis." (PMID 36139553, 2022). "In addition, we also further scrutinized the mutation pattern of ALPK1 in the colorectal cancers of a Taiwanese cohort by using HRM analysis." (PMID 27283888, 2016). "In conclusion, we show that various species of the Fusobacterium genus are able to activate ALPK1 in colorectal cancer cells via the release of ADP-heptose or other ALPK1-activating heptose phosphates into its environment." (PMID 39881579, 2025). "A pilot study showed that mRNA overexpression of ALPK1 affected the migration of lung and colorectal cancer cells, but this finding was inconsistent between cancer cell lines and cancer tissues from clinical patients." (PMID 36139553, 2022). "The fact that the expression of ALPK1 is related to inflammation and various diseases, like lung and colorectal cancer tissue has been the concentration of recent studies." (PMID 29443735, 2018). "In lung and colorectal cancer tissues, the ALPK1 RNA level of the normal part was higher than that of the tumor part using the RT-qPCR analysis." (PMID 27283888, 2016). "The results indicated that, in comparison to samples of adjacent normal tissue, both the lung and colorectal cancer tissues exhibited lower mRNA expression of ALPK1." (PMID 27283888, 2016). "A very recent study shows evidence of a correlation of ALPK1 mRNA expression with tumorigenesis in lung and colorectal cancer." (PMID 27829216, 2016). "ALPK1 activation of NF-κB leads to spiradenomas or colorectal cancer." (PMID 36139553, 2022). "With a view to testing whether ALPK1 could be involved in the progression of cancer, RT-qPCR (reverse-transcription quantitative polymerase chain reaction) assays were performed to determine the expression of ALPK1 in lung and colorectal cancer tissues." (PMID 27283888, 2016). "Thus, ALPK1 might play a key role in the prognosis or diagnosis of colorectal cancer due to its effects on cancer progression." (PMID 27283888, 2016). "F. nucleatum can also induce alpha-kinase 1 (ALPK1) to stimulate the NF-κB pathway, leading to the upregulation of intercellular adhesion molecule 1 (ICAM1) and metastasis of colorectal cancer (CRC)." (PMID 39456558, 2024). "Another recent study on colorectal cancer metastasis found that F. nucleatum induced a novel pattern recognition receptor, ALPK1, to activate the NF-κB pathway, gave rise to upregulation of ICAM1, which in turn enhanced the adhesion of colorectal cancer cells to endothelial cells." (PMID 37148441, 2023).
spiradenoma (9 papers, 2019 to 2025). "A recurrent mutation, p.V1092A, in ALPK1 has also been identified in spiradenoma and spiradenocarcinoma, two forms of skin cancers with sweat gland differentiation." (PMID 39868044, 2025). "In contrast, ALPK1[Val1092Ala] is a driver mutation of a rare type of hair follicle tumour called spiradenoma, which can transform into an invariably fatal form known as spiradenocarcinoma." (PMID 39600975, 2024). "The spiradenoma-causing ALPK1[V1092A] mutant was not only activated by these three nucleotide sugars but also by GDP-α-D-mannose (and weakly by UDP-α-D-galactose)." (PMID 38060563, 2023). "We found that combining the ALPK1[R153A] mutation with the spiradenoma mutant or the ROSAH mutant did indeed prevent activation by UDP-α-D-mannose, GDP-α-D-mannose, ADP-D-ribose, cyclic ADP-D-ribose, and UDP-α-D-galactose in vitro." (PMID 38060563, 2023). "Using whole-exome sequencing, the authors identified a recurrent missense mutation (V1092A) in the C-terminal kinase domain of ALPK1 gene in the spiradenomas and spiradenocarcinomas; this mutation activated the NF-κβ pathway in a reporter assay." (PMID 36139553, 2022). "Most spiradenomas, however, harbored ALPK1 mutations, which were mutually exclusive from CYLD mutations." (PMID 32461623, 2020). "We next focused on genes identified from our analysis of the discovery cohort, revealing ALPK1 p.V1092A mutations in one cylindroma–spiradenoma hybrid, two low-grade spiradenocarcinomas, and one spiradenoma." (PMID 31101826, 2019). "We discovered a recurrent somatic hotspot mutation in the alpha-kinase domain of the ALPK1 gene (p.V1092A) in 7/16 spiradenomas, 2/8 high-grade, and 2/6 low-grade spiradenocarcinomas from our discovery cohort." (PMID 31101826, 2019). "Notably, we find a recurrent missense mutation in the kinase domain of the ALPK1 gene in spiradenomas and spiradenocarcinomas, which is mutually exclusive from mutation of CYLD and can activate the NF-κB pathway in reporter assays." (PMID 31101826, 2019). "Notably, ALPK1 was recurrently mutated at a hotspot position and was reported as a driver event in both spiradenoma (both methods) and spiradenocarcinoma (only by IntOGen), and is discussed in detail below." (PMID 31101826, 2019). "Notably, we find a hotspot driver mutation in ALPK1 that defines spiradenoma and spiradenocarcinoma cases." (PMID 31101826, 2019). "Specific mutations in ALPK1 are associated with an autoinflammatory syndrome termed ROSAH and with spiradenoma (skin cancers with sweat gland differentiation)." (PMID 39868044, 2025). "Altogether, we showed that several ALPK1 mutants associated with diseases have an altered ADPH-induced kinase activity and that the V1092A mutant, more particularly associated with spiradenoma and spiradenocarcinoma, induces massive assembly of TIFAsomes in a constitutive manner." (PMID 37072480, 2023). "Interestingly, p.V1092A spiradenoma mutants have also been shown to have the constitutive activity of ALPK1 and NF-κB signaling in the absence of ADP-heptose." (PMID 37317291, 2023).
Splenomegaly (8 papers, 2019 to 2025). Abnormal increased size of the spleen. "ALPK1 may be important in the development of the red blood cell (RBC) cytoskeleton, which if impaired may lead to the propensity to form elliptocytes noted in one case, and may be filtered at the level of the spleen resulting in splenomegaly." (PMID 30967659, 2019).
chronic kidney disease (7 papers, 2015 to 2025). Impairment of the renal function secondary to chronic kidney damage persisting for three or more months. "The missense variants rs2074379 (M732I) and 2074388 (G565D) of ALPK1 were found to be significantly associated with the prevalence of chronic kidney disease and diabetes in a dominant model, suggesting that the two diseases are closely related." (PMID 36139553, 2022). "One of the ALPK1 missense variants was rs2074388 (G565D) in exon 11, which has also been found in colon cancer, chronic kidney disease, and diabetes." (PMID 36139553, 2022). "The rs2074379 (M732I) and rs2074388 (G565D) of ALPK1 variants were found to be significantly associated with type 2 diabetes, whereas rs2074380 (G870A) and rs2074381 (A916G) were significantly associated with chronic kidney disease and myocardial infarction." (PMID 36139553, 2022). "Previous studies showed ALPK1 is highly associated with inflammatory responses in chronic diseases such as chronic kidney disease (CKD) and type 2 DM." (PMID 36732854, 2023). "A recent genome-wide association study (GWAS) revealed the possible relationship between ALPK1 SNPs and chronic kidney disease (CKD)." (PMID 25326865, 2015).
type 2 diabetes mellitus (6 papers, 2015 to 2023). A type of diabetes mellitus that is characterized by insulin resistance or desensitization and increased blood glucose levels. "ALPK1 was previously identified as a susceptibility gene for CKD among subjects with diabetes mellitus." (PMID 25813695, 2015). "ALPK1 has also been noted as a gene related to the susceptibility to type 2 diabetes mellitus." (PMID 37317291, 2023). "Intriguingly, ALPK1 variant was reported to be associated with type 2 diabetes, suggesting that ALPK1 might also be involved in the injury of pancreatic beta cells in the scenario of type 2 diabetes." (PMID 34621265, 2021). "Therefore, ALPK1 may be a gene indicating susceptibility to type 2 diabetes mellitus." (PMID 36139553, 2022). "Raised renal ALPK1 level in patients with diabetes was reported." (PMID 31557402, 2019). "Whether ALPK1 is involved in diabetes and hyperglycemia is a fascinating topic." (PMID 36139553, 2022).
colitis (5 papers, 2018 to 2024). Inflammation of the colon. "In response to infection with the commensal pathobiont Helicobacter hepaticus (Hh), Alpk1-deficient mice display exacerbated interleukin (IL)-12/IL-23 dependent colitis characterized by an enhanced Th1/interferon(IFN)-γ response." (PMID 30228258, 2018). "In summary, we have identified Alpk1 as a critical determinant of murine colitis susceptibility encoded by the Hiccs and Cdcs1 loci." (PMID 30228258, 2018). "Having found a critical role for Alpk1 in regulating inflammation in a Rag1-deficient setting, we next assessed its impact on lymphocyte-replete colitis." (PMID 30228258, 2018). "We show that Alpk1 deficiency leads to severe colitis and an exaggerated Th1 immune response in mice infected with the intestinal pathobiont Helicobacter hepaticus." (PMID 30228258, 2018). "Thus, Alpk1 deficiency causes a colitis-susceptible phenotype similar to that of 129.Rag2−/− mice, suggesting Alpk1 as a potential regulator of colitis susceptibility in the Hiccs and Cdcs1 loci." (PMID 30228258, 2018). "Thus, loss of Alpk1 function permits aberrant Th1 immunity that, in combination with IL-10 deficiency, causes aggressive and highly destructive colitis." (PMID 30228258, 2018). "Interestingly, at the time that ALPK1 was identified as the cognate receptor of ADP-heptose, Ryzhakov and colleagues reported that Alpk1−/− mice are more susceptible to Helicobacter hepaticus-induced colitis and that this condition is mainly driven by Alpk1 deficiency in hematopoietic cells." (PMID 39288239, 2024). "Knockout of the Alpk1 gene in mice was recently shown to lead to severe colitis when infected with Helicobacter hepaticus." (PMID 32076438, 2020). "Conversely, irradiated WT or Alpk1−/− animals reconstituted with wild-type bone marrow developed comparable levels of colitis, demonstrating that Alpk1 regulates colitis via the hematopoietic compartment." (PMID 30228258, 2018). "Alpk1−/− mice were then bred with C57BL/6 Rag1−/− mice to be tested in the Hh-induced innate colitis model." (PMID 30228258, 2018). "We therefore treated Alpk1+/− and Alpk1−/− mice with Hh and an IL-10R (IL-10 receptor alpha) blocking antibody to induce colitis." (PMID 30228258, 2018). "In keeping with their similar degree of colitis, wild type and Alpk1+/− mice showed comparable T cell phenotypes; only Alpk1−/− mice developed a polarized Th1 response." (PMID 30228258, 2018). "However, although ALPK1 regulates colitis via the haematopoietic compartment during Hh infection, we have shown here that upon C. rodentium infection of C3H/HeN mice, expression of ALPK1 is upregulated in IECs." (PMID 31610608, 2020). "Consistent with their increased colitis, Alpk1−/− mice also displayed moderate splenomegaly." (PMID 30228258, 2018). "Interestingly, only complete Alpk1 deficiency resulted in exacerbated pathology, as heterozygous (Alpk1+/−) and wild-type (Alpk1+/+) littermates displayed comparably modest colitis." (PMID 30228258, 2018). "However, compared to WT or heterozygous controls, intestinal CD4+ T cells of Alpk1−/− mice were highly skewed towards a Th1 phenotype (IFN-γ+ IL-17A–) following induction of colitis, as measured by cell frequency and IFN-γ expression per cell." (PMID 30228258, 2018). "However, transfer of WT T cells to Alpk1−/−Rag1−/− or Alpk1+/−Rag1−/− hosts resulted in equivalent T-cell differentiation and severity of colitis." (PMID 30228258, 2018). "RAG1 KO mice develop colitis spontaneously upon infection with H. hepaticus, which is exacerbated in RAG1/ALPK1 double KO mice." (PMID 36098982, 2022). "Thus, Alpk1 deficiency in the absence of a strong microbial driver does not appear to significantly impact CD4+ T-cell differentiation or susceptibility to T-cell-driven colitis." (PMID 30228258, 2018). "In contrast, ALPK1 did not affect the nonhematopoietic compartment in a H. hepaticus-induced colitis mouse model." (PMID 32076438, 2020).
colitis (continued). "We demonstrate that Alpk1-deficient mice infected with a pathobiont Helicobacter hepaticus (Hh) develop an unusually potent Th1 CD4+ T-cell response and exacerbated colitis in the absence of IL-10 signalling." (PMID 30228258, 2018). "Therefore, both IL-12 and IL-23 are non-redundant drivers of Hh-induced colitis in Alpk1−/−Rag1−/− mice." (PMID 30228258, 2018). "Although Hh infection of Alpk1−/− mice resulted in marked skewing of T cell differentiation towards Th1 cells in the colon compared to wild-type mice this was not sufficient to result in severe colitis." (PMID 30228258, 2018). "Indeed, our bone marrow chimera studies indicate that Alpk1 expression by hematopoietic, but not epithelial cells, is important for control of Hh-induced colitis in vivo." (PMID 30228258, 2018).